MIF (macrophage migration inhibitory factor)
Diseases named in the same sentence as MIF in open-access papers (continued):
Sharing a sentence is not in itself a finding about the gene and the disease.
malaria (38 papers, 2006 to 2026). Malaria is a serious and sometimes fatal disease caused by a parasite that commonly infects a certain type of mosquito which feeds on humans. "Plasma MIF (macrophage migration inhibitory factor), another pro-inflammatory cytokine, is also enhanced in malaria-infected patients and is associated with the severity of anemia." (PMID 36361552, 2022). "For example, low levels of IL-12 and high levels of MIF have been shown to be associated with severe malaria." (PMID 36093199, 2022). "That is, MIF production has been linked to pathology during malaria and T. brucei infection, by promoting inflammation-induced tissue damage." (PMID 31497025, 2019). "Further, diplotype (MIF-794CATT and rs34383331T > A) 5 T confers protection to severe malaria (OR = 0.55, p = 0.002) while 6A (OR = 3.07, p = 0.001) increases malaria risk." (PMID 24066864, 2013). "MIF was shown to be induced in response to P. chabaudi infection in mice and was implicated in the pathogenesis of malaria anemia." (PMID 23272137, 2012). "The potential role of MIF in the pathogenesis of malaria anaemia became apparent in an experimental study using a mouse model in which high MIF levels were associated with malaria anaemia." (PMID 21929748, 2011). "The elevated level of MIF, an important immune molecule in humans, was reported to be a possible risk factor for death in patients with CM, making it a potential molecular target for improving severe malaria." (PMID 36033889, 2022). "Furthermore, MIF is clearly linked to pathogenesis during other parasitic infections, such as Chagas’ disease and malaria, or viral infections, such as COVID-19, and endotoxic/septic shock resulting from bacterial infection." (PMID 35464430, 2022). "In addition, CXCR4 was identified as an important surface recognition molecule in patients suffering from severe malaria, in whom it functions by releasing macrophage migration inhibitory factor (MIF), which in turn causes NET formation." (PMID 34804066, 2021). "Additionally, studies showed high expression MIF alleles to be associated with increased severity of anemia during malaria." (PMID 32244916, 2020). "In addition, several studies have demonstrated the functional significance of MIF gene polymorphism with malaria severity and pathogenesis in different ethnic populations across the globe." (PMID 24066864, 2013). "In addition, this study also observed that the MIF polymorphism is associated with malaria pathogenesis in Orissa and Chhattisgarh populations of India." (PMID 24066864, 2013). "Therefore, this study investigated the possible association between MIF gene polymorphism and P. falciparum malaria outcome in a well-defined ethnically matched case–control cohort from Orissa and Chhattisgarh, the malaria endemic states of India." (PMID 24066864, 2013). "In addition, it has been observed that the higher MIF-794CATT repeats (>5) increases malaria risk (OR = 1.61, p = 0.01)." (PMID 24066864, 2013). "In addition, the study shows that the higher MIF-794CATT repeats (>5) is a risk factor for severe malaria." (PMID 24066864, 2013). "In malaria, variations in the expression of MIF have been associated with susceptibility to high density parasitemia, while reduced MIF production may lead to increased severity of disease." (PMID 17645880, 2007). "Interestingly, the frequency of the shortest CATT-5 repeat was greatest in African populations, leading to the speculation that MIF low expression alleles may be protective against malaria, similar to the effect seen with sickle hemoglobin (HbS) genes." (PMID 27014277, 2016). "In this study, the possible effect of MIF variations on malaria susceptibility was investigated by re-sequencing the complete MIF gene along with 1 kb each of 5′ and 3′ region in 425 individuals from malaria endemic regions of the Orissa and Chhattisgarh states of India." (PMID 24066864, 2013).
malaria (continued). "MIF regulates both adaptive and innate immune responses and contributes to the pathogenesis of parasitic infections, including malaria." (PMID 42084947, 2026). "However, whether MIF deficiency is likely to play a beneficial role in malaria by upregulating the abundance of producers of short-chain fatty acids or otherwise exert adverse effects through other pathways, as previously reported or in an unknown way, still needs further exploration." (PMID 36033889, 2022). "In contrast, another study revealed that MIF had a protective role in CM, implying that MIF probably has both protective and adverse effects against malaria." (PMID 36033889, 2022). "Conversely, another study found that MIF had a protective role in CM, implying that MIF probably has both protective and adverse effects against malaria." (PMID 36033889, 2022). "Some studies report that Plasmodium infection induces high levels of MIF in humans or mice and suggest that the proinflammatory response promoted by MIF is responsible for the pathology, severe malaria, and fatal outcomes." (PMID 36093199, 2022). "In the case of malaria, MIF-KO mice were found to be protected from infection with Plasmodium chabaudi, with improved Th1-type response and reduced anemia." (PMID 32244916, 2020). "This is in contrast to a recent report showing that MIF is detrimental in an experimental model of malaria and that MIF neutralization has a protective effect." (PMID 32797076, 2020). "The pleiotropic nature of MIF likely affects malaria pathogenesis in multiple ways other than triggering NET release." (PMID 32797076, 2020). "Global analysis of the BAFF-var allele on total RNA expression revealed many differentially expressed genes implicated in the immune response to malaria; among them, we selected CXCL10, CR1, MIF, ICAM-1, and NFKB2 for further analysis." (PMID 33123155, 2020). "In cooperation with IL-12, MIF is important for survival in children with malaria and trypanosoma infection." (PMID 29848367, 2018). "Studies have also shown that MIF is increased in the placenta of malaria-infected women and is thought to be produced by leukocytes in the intervillous space." (PMID 29884801, 2018). "At concentrations found in the circulation of malaria infected patients, MIF was found to suppress erythropoietin-dependent erythroid colony formation." (PMID 27034825, 2016). "Perhaps the high levels of MIF levels observed (by the later studies) in the placenta of women positive for malaria is induced by the malaria parasites that accumulated in the placenta, with MIF helping to retain macrophages in the placenta." (PMID 27239271, 2015). "In a mouse model of malaria using P. berghei, the parasite ortholog of macrophage migration inhibitory factor (PMIF) induced the upregulation of T-bet and IFN-γ and the downregulation of IL-7R, IL-7, IL-2 and Bcl-2 in T cells specific for the parasite." (PMID 25559491, 2015). "A proinflammatory cytokine, macrophage migration inhibitory factor (MIF) is suggested as a factor involved in the pathogenesis of malaria during pregnancy." (PMID 27239271, 2015). "MIF was shown to be highly elevated in the placenta of pregnant women with malaria and other intrauterine infections and in peripheral serum of women with preeclampsia." (PMID 23272137, 2012). "Human studies conducted on African children reported lower levels of MIF in malaria infected children compared with healthy asymptomatic children." (PMID 21929748, 2011). "The Macrophage migration inhibitory factor (MIF) has also been suggested to have a protective role in pathogenesis of malaria." (PMID 21929748, 2011). "For instance, in children with acute malaria circulating MIF levels were significantly lower compared with healthy, malaria-exposed children." (PMID 20169062, 2010). "Elevated MIF levels were observed in malaria infected Zambian children compared to uninfected children." (PMID 19284533, 2009).
malaria (continued). "The potential role of MIF in the pathogenesis of malaria anemia was evident from an experimental study using a mouse model in which high MIF levels were associated with malaria anemia." (PMID 19284533, 2009). "Martiney and co-workers found that MIF was enhanced in a mouse malaria model, and that rMIF inhibited the formation of erythroid (BFU-E), multipotential (CFU-GEMM), and granulocyte-macrophage (CFU-GM) progenitor-derived colonies in vitro." (PMID 17029647, 2006). "There is no consensus on the role of macrophage migration inhibitory factor (MIF) in severe malaria as some studies reported Plasmodium infection induces high levels of MIF in humans or mice while other studies showed low MIF production increases severity of malaria infection." (PMID 41461395, 2026). "Some research suggests that Plasmodium infection increases MIF levels in humans and mice, indicating that the pro‐inflammatory response triggered by MIF may lead to pathology, severe malaria, and fatal outcomes." (PMID 41171200, 2025). "The results may bear the expectation that a synergistic treatment of MIF and intestinal flora can more effectively improve the severity of malaria in malaria treatment targeting MIF in the future." (PMID 36033889, 2022). "Targeting NETs with DNAse treatment resulted in accelerated mortality, suggesting that MIF may play a protective role in malaria." (PMID 32797076, 2020). "Also, circulating serum P. falciparum MIF levels positively correlated with serum TNF-α levels in malaria patients, and higher P. falciparum MIF levels were observed in patients with severe malarial anemia and cerebral malaria." (PMID 31497025, 2019). "Consistent with the role of MIF as erythropoietic suppressor, the elevated serum MIF levels were found in patients with severe malaria; however decreased serum concentration was observed in Kenyan children with malaria." (PMID 27034825, 2016). "Several studies have demonstrated the role of MIF in modulating malaria severity and pathogenesis." (PMID 27239271, 2015). "We hypothesize that the increased MIF levels found in the placenta of malaria positive women is induced by the malaria parasites which tend to accumulate in the placenta and that this may help to retain macrophages in the placenta." (PMID 23272137, 2012). "Thus, future studies are required to define the role of host and Plasmodium MIF in the pathogenesis of malaria." (PMID 22496958, 2012). "Although the reasons for the down regulation of MIF in malaria patients is not well understood, a recent study suggest that this may be due to the decrease in the number of circulating lymphocytes observed during malaria infection." (PMID 19284533, 2009). "However, most human studies conducted with African children have reported lower levels of MIF in malaria infected children compared to healthy asymptomatic children." (PMID 19284533, 2009). "Furthermore, macrophages release MIF in response to malarial pigment, which inhibits erythroid progenitor‐derived colony formation, potentially impacting erythropoiesis and contributing to the pathophysiology of malaria anemia." (PMID 41171200, 2025). "However, as a key rationale for the development of MIF-targeted therapeutic regimens, the role and mechanism of MIF in the regulation of malaria, especially CM, remain unclear." (PMID 36033889, 2022). "However, other studies are in contradiction with this hypothesis, and rather suggest a link between higher MIF levels and severe malaria." (PMID 35464430, 2022). "A similar rationale may be applied to the role of MIF in malaria." (PMID 32797076, 2020). "However, to the best of knowledge no studies have documented the role of MIF gene polymorphism to the development of malaria in Indian populations." (PMID 24066864, 2013).
malaria (continued). "Interestingly, this is the first study which shows that the genotype and allele distribution of rs34383331T > A, present in an uncharacterized ncRNA (LOC284889) and located on the reverse strand to MIF, differ significantly between malaria cases and asymptomatic control groups." (PMID 24066864, 2013). "In fact, PBMC from malaria-naïve patients can react to hemozoin by either increasing or decreasing MIF production, depending on whether they have a generally well-preserved MIF production." (PMID 22496958, 2012). "Furthermore, an inverse correlation between MIF plasma concentrations and hemozoin accumulation was showed in children affected by severe anemia indicating that, different from mouse models, hemozoin may decrease MIF production in human malaria." (PMID 22496958, 2012). "Plasmodium species produce an ortholog of the cytokine macrophage migration inhibitory factor, PMIF, which modulates the host inflammatory response to malaria." (PMID 30006528, 2018). "TGF-β1 has been reported to be induced by MIF in IgA nephropathy while reduced TGF-β1 and increased MIF has been described in severe malaria." (PMID 22065919, 2011). "Rodent malaria parasites can activate mouse macrophages to produce the cytokines IL-12, TNF-α and MIF probably via recognition of parasite ligands by pattern-recognition receptors (PRRs)." (PMID 18439291, 2008). "In this study, the levels of MIF in the peripheral, cord and placental intervillous blood (IVB) plasma collected from women residing in a malaria endemic region of Central India was determined and its association with malaria in pregnancy and birth outcomes was investigated." (PMID 23272137, 2012). "MIF, together with other proinflammatory factors such as IFN-γ and TNF-α, may then activate these macrophages to clear and kill malaria parasites in the placenta." (PMID 23272137, 2012). "Unlike in CMNS patients, higher levels of MIF appear to confer protective advantage to severe malaria anemia patients." (PMID 19284533, 2009). "The malaria placental infections in the current study were past infections and this could explain the lack of significant difference in MIF levels." (PMID 27239271, 2015). "Intriguingly, these comatose malaria cases with no appreciable change in their brains nevertheless showed appreciable systemic evidence of inflammation, as demonstrated by the marked evidence of iNOS, MIF and HO-1 expression elsewhere." (PMID 17029647, 2006). "Numerous studies have shown that Plasmodium infection induces high levels of MIF in humans or mice and have suggested that the proinflammatory response promoted by MIF might affect the outcomes of Plasmodium infection; however, there is no consensus on the role of MIF in severe malaria." (PMID 36093199, 2022). "MIF protein levels were slightly but significantly higher in uRBC-WT versus iRBC-WT, while in BAFF-var cells, MIF levels were overall higher and did not increase further upon exposure to malaria antigens." (PMID 33123155, 2020).
myocardial infarction (37 papers, 2013 to 2025). Gross necrosis of the myocardium, as a result of interruption of the blood supply to the area, as in coronary thrombosis. "This study demonstrated a significant positive association between MIF gene polymorphism and the occurrence of cardiovascular events like myocardial infarction, with a statistically significant p-value (p=0.001)." (PMID 39439602, 2024). "The study showed a statistically significant positive correlation (p=0.001) between the MIF gene polymorphism and the incidence of cardiovascular events such as myocardial infarction." (PMID 39439602, 2024). "In contrast, mice with MIF WT bone marrow and MIF KO cardiac myocytes had an increased risk of cardiac rupture after myocardial infarction even more than wild type mice." (PMID 29084983, 2017). "MIF also causes degradation of elastin and collagen within the plaque, which is responsible for unstable plaque formation and plaque rupture; this goes on to block the coronary vessels, resulting in acute myocardial infarction." (PMID 39439602, 2024). "MIF promotes cardiac fibroblast proliferation through the Src kinase signaling pathway, induces proinflammatory gene expression during myocardial infarction (MI), and promotes survival via CXCR4/AKT signaling." (PMID 40092999, 2025). "In the case of acute myocardial infarction, MIF increased in myocytes within a few hours, preceding macrophage infiltration in the infarcted area." (PMID 39062865, 2024). "A recent study showed that macrophage migration inhibitory factor facilitates the therapeutic efficacy of mesenchymal stem cells derived EVs in acute myocardial infarction through upregulating miR-133a-3p." (PMID 36696015, 2023). "Paradoxically, other study reported that MIF improve myocardial infarction by suppressing oxidative stress and apoptosis." (PMID 36160453, 2022). "Taken together with our data, these results would have implied that MIF has more therapeutic potential in ischemic stroke than in myocardial infarction." (PMID 33672416, 2021). "BMSC-Exos with high expression of macrophage migration inhibitory factor (MIF) has a protective effect on the heart of rats with myocardial infarction." (PMID 34631718, 2021). "The physiological concentration of MIF in patients with myocardial infarction is reported as 1.5–30 ng/mL; thus, the cardioprotective effects of MIF at different concentrations (1, 10, 50, and 1000 ng/mL) were explored." (PMID 33672416, 2021). "Macrophage migration inhibitory factor (MIF) is involved in multiple CVDs, including myocardial infarction." (PMID 31964409, 2020). "The source of elevated MIF levels in patients with myocardial infarction was mainly necrotic cardiomyocytes." (PMID 30983881, 2019). "During events such as acute myocardial infarction, hypoxia and oxidative stress induce the release of MIF from cardiomyocytes." (PMID 30057807, 2018). "After myocardial infarction, having MIF WT cardiac myocytes and MIFKO bone marrow was cardioprotective, even more than global MIFKO in both compartments." (PMID 29084983, 2017). "In patients with acute myocardial infarction, circulating MIF was rapidly released and MIF protein levels were found elevated." (PMID 29027966, 2017). "In their murine myocardial infarction model they explored the importance of MIF expressed by the stromal cell compartment of the damaged tissue (cardiac myocytes) versus the bone-marrow-derived cell compartment." (PMID 29084983, 2017). "So far, circulating MIF protein present in plasma after myocardial infarction or in atherogenic vessels has been considered being mainly secreted by endothelial cells, cardiomyocytes or circulating leukocytes." (PMID 26485680, 2015). "We determined changes in circulating MIF levels, explored the cellular source of MIF, and studied the role of MIF in mediating inflammatory responses following acute myocardial infarction (MI)." (PMID 24098445, 2013).